ANKRD36 (ankyrin repeat domain 36)
Synonyms: UNQ2430
Tractability: PROTAC: ubiquitination databases record sites on it.
Gene: Protein-coding gene on chromosome 2 (97,113,153 to 97,264,521, forward strand). Ensembl gene ENSG00000135976.
Subcellular location (Human Protein Atlas): Cytosol; Nucleoplasm
Genetic constraint (gnomAD): Loss-of-function variants: 162 observed, 162.99 expected, observed/expected ratio (o/e) 0.99, 90% interval 0.87 to 1.13. The synonymous counts are far from expectation, so gnomAD's model fits this gene poorly and the ratio says little. Missense variants: 1,102 observed, 1,174.7 expected, observed/expected ratio (o/e) 0.94, 90% interval 0.89 to 0.99. Synonymous variants: 299 observed, 380.23 expected, observed/expected ratio (o/e) 0.79, 90% interval 0.71 to 0.87.
Homologues: Orthologues: dog ANKRD31 (8% identical), tropical clawed frog ankrd31 (5% identical), Drosophila melanogaster pain (5% identical). Paralogues in human: ANKRD36C (91% identical), ANKRD36B (64% identical), ANKRD31 (8% identical).
Diseases named in the same sentence as ANKRD36 in open-access papers:
ANKRD36 is named in the same sentence as 20 diseases in open-access papers, as found by Europe PMC text mining. Sharing a sentence is not in itself a finding about the gene and the disease. The quoted sentences say what the papers report.
leukemia (2 papers, 2014 to 2021). A malignant (clonal) hematologic disorder, involving hematopoietic stem cells and characterized by the presence of primitive or atypical myeloid or lymphoid cells in the bone marrow and the blood. "We searched “The Cancer Genome Atlas (TCGA)” of the National Cancer Institute of the National Institute of Health (Bethesda, MD, USA) and “cBioPortal for Cancer Genomics” to find any leukemia-specific ANKRD36 mutations." (PMID 34827175, 2021). "Nevertheless, we could not find ANKRD36 mutations related to any type of leukemia." (PMID 34827175, 2021).
type 2 diabetes mellitus (2 papers, 2019 to 2021). A type of diabetes mellitus that is characterized by insulin resistance or desensitization and increased blood glucose levels. "In type 2 diabetes mellitus patients (T2DM), ANKRD36 expression was found to be significantly upregulated as compared to normal controls." (PMID 34827175, 2021).
breast carcinoma (1 paper, 2020). "Additional findings that are noteworthy are that we identified the 39 most frequently mutated genes in CTCs and metastases, and some of them such as MUC16, ANKRD36, and DNAH5 are known to be biologically important in breast cancer." (PMID 32650480, 2020).
gastric cancer (1 paper, 2021). A primary or metastatic malignant neoplasm involving the stomach. "In another study, the mutational status of ANKRD36 genes was found to be correlated with proximal gastric cancer." (PMID 34827175, 2021).
myocarditis (1 paper, 2025). Myocarditis is a condition that is characterized by inflammation of the heart muscle (myocardium). "In patients with pneumonia and myocarditis, ANKRD36 plays a proinflammatory role by regulating intracellular NF-κB inflammation-related pathways." (PMID 40087743, 2025).
polycystic ovary syndrome (1 paper, 2024). A disorder that manifests as multiple cysts on the ovaries. "DEGs for the Dormant (O1) subcluster encompass Ankrd36, whose mutation has been implicated in diminished ovarian reserve, as well as Pm20d1, which has been noted for its potential involvement in the pathogenesis of polycystic ovary syndrome." (PMID 39441825, 2024).
psoriasis (1 paper, 2020). An autoimmune condition characterized by red, well-delineated plaques with silvery scales that are usually on the extensor surfaces and scalp. "We further found that a sub-cluster of T cells, which express NR4A1, a transcription factor indicative of dysfunctional T cells, and are enriched for genes involved in nuclear organization (NEAT and ANKRD36), was over-represented in psoriasis samples." (PMID 33053333, 2020).
renal cell carcinoma (1 paper, 2021). "A study analyzing the antitumor role of miR-144-5p in renal cell carcinoma (RCC) showed that the ANKRD36 gene is targeted by miR-144-5p." (PMID 34827175, 2021).
cancer (5 papers, 2014 to 2025). A tumor composed of atypical neoplastic, often pleomorphic cells that invade other tissues. "All these studies highlight the significance of ANKRD36 in important biological functions and its association with cancer, as well as showing that this gene is targetable and druggable if found mutated." (PMID 34827175, 2021). "ANKRD36 has been reported to be coexpressing and interacting with other genes on locus 2q11.2, including ANKRD36C, ITPRIPL1, FAHD2B, FAM178B and CNNM3, which shows that ANKRD36 is involved in some important biological networks associated with cancers." (PMID 34827175, 2021). "Moreover, it also indicates that silencing of ANKRD36 miR-182 and miR-144-5p can suppress tumor growth and increase the apoptotic activity of the cancer cells." (PMID 34827175, 2021). "Thus, inhibition of miR-182 and miR-144-5p might be important drug targets to find a new treatment for advanced phases of cancers where ANKRD36 has some role, including CML." (PMID 34827175, 2021). "However, various studies have found a role of ANKRD36 in different cancers." (PMID 34827175, 2021). "In these ceRNA triplets, miR-484, miR-181a-5p, miR-423-5p and let-7b-5p were identified as miRNA biomarkers with excellent distinguishing ability between normal and tumor tissues, and ANKRD36, PCGF2, EZH2 and ATP6V1F were closely related to the prognosis of corresponding cancer." (PMID 33194594, 2020). "ANKRD36′s main function and exact role in CML or any other cancer are still unknown." (PMID 34827175, 2021).
tumor (5 papers, 2020 to 2025). "For example, TTN and ANKRD36, both highly mutated in deceased patients and listed among the top-ranked genes, are associated with cytoskeletal reorganization and structural maintenance, critical processes for tumor invasion and metastasis." (PMID 40722723, 2025). "Data from miRTarBase database of micro-RNAases shows that ANKRD36 is also regulated by miR-182, which is a miRNA expressed in the early stages of tumor growth." (PMID 34827175, 2021). "The events that showed the most decreased PSI in the tumor were those in ANKRD36 (an uncharacterized gene with an ankyrin repeat domain), LMO7 (PDZ and the LIM domain-containing), and NKTR (facilitates natural killer cell binding to targets)." (PMID 34440489, 2021).
ANKRD36 also shares sentences with these, for which no sentence is quoted: colon cancer (2 papers); rectal cancer (2); atherosclerosis (1); autoimmune disease (1); Chronic Myeloid Leukemia (1); colorectal cancer (1); diabetic kidney disease (1); inflammatory bowel disease (1); ovarian yolk sac tumor (1); pneumonia (1).